SPACA5B (sperm acrosome associated 5B)
Synonyms: LYZL5B
Tractability: Antibody: UniProt places it where antibodies can reach, with high confidence; UniProt predicts a signal peptide or a membrane-spanning region; its Gene Ontology location is reachable by antibodies, with medium confidence.
Gene: Protein-coding gene on chromosome X (48,130,626 to 48,132,620, forward strand). Ensembl gene ENSG00000171478.
Subcellular location: Secreted
Gene Ontology:
Molecular function: lysozyme activity
Biological process: fusion of sperm to egg plasma membrane involved in single fertilization
Cellular component: acrosomal vesicle; sperm flagellum; extracellular region
Homologues: Orthologues: chimpanzee SPACA5 (100% identical), macaque SPACA5 (97% identical), pig SPACA5 (79% identical), dog SPACA5 (77% identical), rabbit LYZE (75% identical), rat Spaca5 (75% identical), guinea pig LYZE (74% identical), mouse Spaca5 (70% identical), Drosophila melanogaster CG8492 (38% identical), Drosophila melanogaster CG7798 (31% identical), Drosophila melanogaster CG30062 (30% identical), Drosophila melanogaster CG11159 (30% identical), and 8 more. Paralogues in human: SPACA5 (100% identical), LYZL1 (42% identical), SPACA3 (42% identical), LYZL2 (41% identical), LYZ (40% identical), LYZL6 (40% identical), LYZL4 (34% identical), LALBA (28% identical).